TNF (tumor necrosis factor)
Diseases named in the same sentence as TNF in open-access papers (continued):
Sharing a sentence is not in itself a finding about the gene and the disease.
enteropathy (23 papers, 1995 to 2025). "We assessed the protein and mRNA levels of TNF-α, another key cytokine in enteropathy-associated inflammation." (PMID 37816857, 2024). "Regarding phenotype, patient 2.1, carrier of a de novo insertion (p.Ala110Argfs*48), suffered Crohn’s like enteropathy treated for a long time with anti-TNF therapy, and represents a good example of enteropathy associated with IRF2BP2-CVID." (PMID 37876937, 2023). "In NAIP/NLRC4-deficient mice, S.Tm elicited severe enteropathy within 72 h, characterized by elevated mucosal TNF (>20 pg/mg) production from bone marrow-derived cells, reduced regeneration, excessive enterocyte loss, and a collapse of the epithelial barrier." (PMID 33731826, 2021). "Moreover, TNF-α, directly linked to the pathogenesis of enteropathy, binds to TNF-RI cell death receptors leading to hepatocyte apoptosis followed by accumulation of neutrophils." (PMID 23573127, 2013). "TNF also can cause enteropathy directly, which may accelerate the process of bacterial translocation." (PMID 19014537, 2008). "Cases of patients 4 and 7 are particularly informative, as anti-TNF-α therapy was necessary to achieve remission of a self-sustaining enteropathy after olmesartan discontinuation." (PMID 26101883, 2015). "The evidence that normal mice injected with TNF-α develop severe enteropathy and the rapid response of ILCs to poly I:C administration with increased TNF-α production suggest a possible role for ILCs in the early phases of tissue damage in CD." (PMID 25950701, 2015). "B. longum CECT 7347 administration increased NFκB expression and IL-10, but reduced TNF-α, production in the enteropathy model." (PMID 22348021, 2012). "The administration of B. longum CECT 7347 to the enteropathy model significantly reduced TNFα (P = 0.003) and increased IL-10 (P<0.001) production, indicating its ability to counteract the inflammatory response in the intestinal mucosa." (PMID 22348021, 2012). "Enteropathy secondary to olmesartan therapy results from the drug’s ability to induce T-cell activation and dysregulate cytokines, including tumor necrosis factor alpha (TNF-α) and interferon gamma (IFN-γ)." (PMID 40724600, 2025). "Therefore, it is possible that the B. longum strain used in this study only causes a transient activation of NF-kB mRNA expression without enhancing the final production of inflammatory mediators such as TNF-α in the enteropathy animal model." (PMID 22348021, 2012). "Considering the clinical data (CVID patient with enteropathy), we tested whether the vigorous responses of the CXCL16high B cells were dependent on TNF-α." (PMID 22454615, 2012). "In indomethacin-induced enteropathy in rats, HBOT reduced the TNF-α expression after 12 hr and 24 hr treatment, but the effect was null after 48 hr." (PMID 35911854, 2022). "When P3 developed enteropathy, he was initially treated with mesalazine, oral steroids, and probiotics cycles; due to lack of clinical response to first line treatment, anti-TNF-α (Infliximab) was undertaken." (PMID 33080915, 2020). "Furthermore, in the gliadin-induced enteropathy animal model, this strain has been shown to reduce the peripheral CD4+ T cells, rise IL-10, and shrink TNF-α production." (PMID 31013929, 2019).
gastric tumor (23 papers, 2011 to 2024). "We found that compared with those in normal samples, gastric tumor samples had significantly increased TNF, NOX4, and LONP1 mRNA levels and decreased DUSP1 mRNA levels." (PMID 38758860, 2024). "TNF-α signaling meditated by TNFR1 in the TME has been reported to promote gastric tumor development and maintain tumor cells in an undifferentiated state." (PMID 38149248, 2023). "TNF-α can act as an endogenous tumor promoter of inflammation, proliferation, cell transformation, survival, angiogenesis, and ultimately gastric tumor carcinogenesis or progression." (PMID 35955936, 2022). "Gastric tumor-derived TNF-α induced CD45RA−CCR7− Treg subset with similar phenotype to their status in tumors and inhibited their HLA-DR expression via activating STAT3 phosphorylation." (PMID 28817117, 2017). "Wnt signaling is reported to be increased by TNFα in gastric tumor cells." (PMID 33193326, 2020). "Furthermore, the downregulation of XIAP-AS1 promotes the apoptosis of gastric tumor cells induced by tumor necrosis factor (TNF)-related apoptosis-inducing ligand (TRAIL) 118,119." (PMID 32754285, 2020). "Moreover, we demonstrated that gastric tumor-derived TNF-α efficiently induced CD45RA−CCR7− Treg subset and inhibited HLA-DR expression on these cells by inducing signal transducer and activator of transcription 3 (STAT3) phosphorylation." (PMID 28817117, 2017). "Taken together, our data demonstrated that gastric tumor-derived TNF-α plays an essential role in the induction of CD45RA−CCR7− Treg subset in vitro, and suggest that a similar process might operate in vivo." (PMID 28817117, 2017). "Interestingly, TNF-α was shown to promote Wnt signaling through translocation of β-catenin into the nucleus in gastric tumor cells." (PMID 27092172, 2016). "Interestingly, TNF-α is known to induce β-catenin nuclear accumulation without APC mutations in gastric tumors." (PMID 27388564, 2016). "To confirm the universality of these expression changes, we measured the levels of CXCR2, KRT14 and TNF-α in SGC 7901 cells, which are also derived from gastric tumors." (PMID 27556695, 2016). "Strikingly, NK cells strongly induced an inflammatory response in response to ZL-1211 treatment, including increased IFNγ, TNFα, and IL6 production, and were recruited into tumor microenvironment in patient-derived gastric tumors expressing CLDN18.2 upon ZL-1211 treatment to lyse the tumor cells." (PMID 36922936, 2022). "In this study, we investigated the gastric tumor response to radiation therapy, based on the Sting signal, IFNB1, TNFα, CXCL-9 as well as IL-10 gene expression, infiltration of DCs, Th and Teff cells in the tumor microenvironment, and PD-1/PD-L1 expression after radiation therapy." (PMID 32960261, 2020). "The current study found that stimulation of PADI4 increased CXCR2, KRT14 and TNF-α expression levels, suggesting that increased expression of PADI4 in gastric tumor tissues, as we previously observed, contributes to tumorigenesis by increasing the expression levels of CXCR2, KRT14 and TNF-α." (PMID 27556695, 2016).
hypertrophic cardiomyopathy (23 papers, 2016 to 2025). A condition in which the myocardium is hypertrophied without an obvious cause. "This is in line with several studies that reported elevated levels of circulating inflammatory markers, including tumor necrosis factor and IL-6, in hypertrophic cardiomyopathy (HCM), supporting the anti-inflammatory role of these treatments in cardiac health." (PMID 38813367, 2024). "In KEGG enrichment analysis, the targets of PM2.5 were considerably enriched to various biological processes, including Ferroptosis, TNF signaling pathway, Hypertrophic cardiomyopathy, Cardiac muscle contraction, Glutathione metabolism, and so forth." (PMID 38007415, 2023). "Hypertrophic cardiomyopathy, the TNF signaling pathway, and chemical carcinogenesis were significantly enriched KEGG pathways." (PMID 36685910, 2022). "Hypertrophic cardiomyopathy (p = 6.54E-04), the TNF signaling pathway (p = 1.75E-03), and chemical carcinogenesis (p = 6.95E-03) were significantly enriched KEGG pathways." (PMID 36685910, 2022). "All DEGs were annotated and enriched based on their KEGG pathways, and the Log2Q values and enrichment factors of the TNFα signalling, hypertrophic cardiomyopathy, lysosome and oxytocin signalling pathways were significantly enriched." (PMID 31657084, 2020). "The results suggested that the DEGs were majorly involved in Ferroptosis, MAPK signaling pathway, Viral carcinogenesis, Apoptosis, HIF-1 signaling pathway, TNF signaling pathway, Hypertrophic cardiomyopathy, Cardiac muscle contraction, FoxO signaling pathway, and Glutathione metabolism." (PMID 38007415, 2023). "Moreover, pathways of upregulated DEGs in L. brandtii were involved in the immune, endocrine, and cardiovascular systems [e.g., NOD-like receptor signaling pathway, TNF signaling pathway, hypertrophic cardiomyopathy (HCM), and melanogenesis]." (PMID 32256671, 2020). "For HT vs. DLT, 15 pathways were significantly enriched (p < 0.05), including the “hypertrophic cardiomyopathy (HCM)”, “cardiac muscle contraction”, and “TNF signaling” pathways." (PMID 37628600, 2023). "Pathway enrichment assessments determined that the top five enriched pathways were arrhythmogenic right ventricular cardiomyopathy (ARVC), hypertrophic cardiomyopathy (HCM), pathways in cancer, TNF signalling pathway and steroid hormone biosynthesis." (PMID 33960101, 2022). "Studies indicate elevated levels of cytokines like TNF-α, hs-CRP, and inflammatory interleukins (e.g., IL-1β, IL-1RA, IL-6, IL-10, circulating monocyte chemoattractant protein resulted in a chronic low-grade inflammatory state in hypertrophic cardiomyopathy (HCM)." (PMID 38533084, 2024). "Finally, we performed the functional enrichment analysis and found that arrhythmogenic right ventricular cardiomyopathy (ARVC), hypertrophic cardiomyopathy (HCM), pathways in cancer, TNF signalling pathway and steroid hormone biosynthesis were the potentially disrupted pathways in RIF patients." (PMID 33960101, 2022).
Mycobacterium infection (23 papers, 2008 to 2025). Infections with bacteria of the genus Mycobacterium. "Biological agents such as tumor necrosis factor-α inhibitors are known to cause mycobacterium infections." (PMID 24576098, 2014). "Other pathways required to control mycobacterial infections involve tumor necrosis factor alpha (TNF-α), which plays a key role in granuloma formation." (PMID 39860371, 2025). "Other pro-inflammatory cytokines such as TNF-α/IL-6 also engaged in limiting Mycobacterium infection." (PMID 36090984, 2022). "IL-1 is known to induce and enhance memory-type immune responses (44, –, 46), whereas TNF-α protects against Mycobacterium infection and plays a functional role in CD4 and CD8 T cell responses to M. tuberculosis infection." (PMID 33692195, 2021). "TNF-α plays a key role in increasing host resistance to Mycobacterium infection during the Th1 response." (PMID 33520738, 2020). "During mycobacterial infection, T cells, macrophages, and dendritic cells produce TNF-α in response to multiple signaling pathways." (PMID 33552087, 2020). "In our research, the level of TNF-α triggered by mycobacterium infection increased with increasing virulence of mycobacterium strains." (PMID 28837698, 2017). "IL-1β is a critical innate cytokine in mycobacterial infection and has complex cross-talk with other mediators within the complex inflammatory network consisting of IL-1β, TNF-α, eicosanoids, chemokines, and Th17 response." (PMID 29228045, 2017). "miR-99b upregulation has been observed to stimulate the production of proinflammatory cytokines such as IL-6, IL-12, IL-1β, and TNF-α in macrophages and DCs upon Mycobacterium infection." (PMID 27803700, 2016). "Mycobacterium infections have been indicated to subvert pro-apoptotic TNF-α signaling by either reduction of TNF-α expression or downregulation of its receptor, as well as differential NF-κB activation." (PMID 19014542, 2008). "Physiological levels of TNF-α have a defensive role against mycobacterial infection." (PMID 37035321, 2023). "However, the role of anti-TNF therapy in clinical cases of mycobacterial infection is controversial." (PMID 33552087, 2020). "TNF blockers have shown some promise as HDTs for mycobacterial infections." (PMID 33552087, 2020). "TNFα, a protective cytokine during early mycobacterial infection, was found reduced with AVP treatment; nevertheless, CVP did not reverse the TNF inhibition mediated by VP completely, suggesting a different mechanism regarding vasopressinergic modulation over macrophage cytokine production." (PMID 31244771, 2019). "In addition, TNF-α has an immune regulatory function that controls Th1 cell activation and immunopathology following pulmonary mycobacterial infection, and it is also a negative regulator of CD4 and CD8 T-cell responses to lymphocytic choriomeningitis virus infection." (PMID 24676272, 2014). "miR-146a modulates the inflammatory response upon Mycobacterium infection in Raw 264.7 cells by targeting IRAK1 and TRAF6, resulting in remarkably reduced translation of IL-6, IL-1β, and TNF-α." (PMID 27803700, 2016).
myelofibrosis (23 papers, 2013 to 2025). A partial or complete replacement of the bone marrow stroma by fibrous tissue. "Moreover, there is a correlation between TNF-α and grade of myelofibrosis, with patients having higher grades of MF associated with serum higher TNF-α." (PMID 38585007, 2024). "Selinexor has also been shown to reduce the plasma levels of many key pro-inflammatory cytokines (e.g., IL-6, TGFβ, IL-1β, IL-10, IFN-γ, TNF-α) in patients with myelofibrosis, and also in ex vivo studies with PBMCs." (PMID 40565816, 2025). "In conclusion, the elevation of serum TNF-α in MPN patients is of diagnostic significance and is correlated with the severity of myelofibrosis." (PMID 38585007, 2024). "The elevation of serum TNF-α in MPN patients is of diagnostic significance and is correlated with the severity of myelofibrosis." (PMID 38585007, 2024). "It is noteworthy that there is a certain correlation between serum TNF-α and the grade of myelofibrosis in MPN and IE/IT patients." (PMID 38585007, 2024). "The highest TNF-α concentrations were seen in patients with myelofibrosis, so it is possible that the mitochondrial mass is influenced by the histological MPN subtype." (PMID 37280424, 2023). "Ruxolitinib alleviates constitutional symptoms of myelofibrosis (MF) by downregulating interleukin (IL)-1b, IL-6 and TNF-α." (PMID 30700842, 2019). "Tumor necrosis factor alpha (TNF) is increased in myelofibrosis (MF) and promotes survival of malignant over normal cells." (PMID 29749399, 2018). "Past studies revealed that STAT3, VEGFA, and TNF also played an important role in the pathogenesis of myelofibrosis." (PMID 30622613, 2018). "We therefore tested whether the mechanism of galectin-1 increase in myelofibrosis might occur secondary to TNF stimulation." (PMID 39383242, 2024). "Activated TNFα pathways were also confirmed by RNA-seq analysis in patients suffering from EZH2- or DNMT3A-deficient myelofibrosis compared to non-mutant controls." (PMID 32604862, 2020). "Use of ruxolitinib in patients with myelofibrosis can cause inhibition of the JAK-STAT signaling, thus leading to depressed T helper cell type 1 response and a reduction of multiple cytokine production including IFN-γ and TNF-α." (PMID 27843657, 2016). "We identified a set of inflammatory cytokines, including IL-1alpha, IL-4, IL-6, IL-7, IL-9, IL-15 and TNF-alpha, which are elevated in the serum of JAK2V617F mice, similar to the alterations in circulating cytokines observed in patients with myelofibrosis." (PMID 40386398, 2025). "Independently of JAK status or of MPN subtype (myelofibrosis or PV), several cytokines were reduced after ruxolitinib treatment such as IL1Ra, IL6, IL8, TNFα, and bFGF." (PMID 26525644, 2015). "Moreover, a correlation between symptomatic reduction of the spleen size in myelofibrosis and reductions of IL-1ra, MIP-1β, IL6, and TNFα was observed." (PMID 26525644, 2015). "Interestingly, we found that ruxolitinib, a specific JAK1/2 inhibitor which used for myelofibrosis treatment, could substantially reduce plasma IL-6, IL-1β, IFN-γ and TNF-α contents in atherosclerotic rabbits." (PMID 32169038, 2020). "Notably, a significant increase in LGALS1 was observed in patients with myelofibrosis due to either JAK2V617F or mutCALR, confirming that basophils and mast cells are likely to play an important role in the pathobiology of myelofibrosis in patients and contribute to TNF pro-inflammatory pathways." (PMID 39383242, 2024). "Patients with primary myelofibrosis, with or without the presence of JAK2V617F, develop a proinflammatory cytokine signature that contains IL-6, MCP-1, MIG, MIP-1α, TNF-α and IP-10." (PMID 24116232, 2013).